BUB1B (BUB1 mitotic checkpoint serine/threonine kinase B)
Diseases named in the same sentence as BUB1B in open-access papers (continued):
Sharing a sentence is not in itself a finding about the gene and the disease.
colorectal cancer (22 papers, 2009 to 2025). A primary or metastatic malignant neoplasm that affects the colon or rectum. "BUB1B expression was significantly lower in colorectal cancer, which was linked to poor prognosis and lymph node metastasis." (PMID 41163302, 2025). "Although scarce, carriers of BUB1B heterozygous deleterious variants have been reported in some cancer patient cohorts, namely, early-onset colorectal cancer, familial pancreatic cancer, and cutaneous melanoma with multiple primary carcinomas." (PMID 39014450, 2024). "Colorectal carcinomas with low BUB1B expression were associated with frequent lymph node metastasis and poor prognosis." (PMID 33431813, 2021). "Nevertheless, despite the potential of spindle checkpoint genes as tumor suppressors and the first validation of a causal link between BUB1B variants and lung and colorectal cancer development in BubR1± mouse models in 2004, the cancer-predisposing role of BUB1B remains largely elusive." (PMID 39014450, 2024). "According to previous reports, mutations in BUB1B were indeed found in patients with colorectal cancer, but further studies are needed to determine whether the mutations increase its carcinogenicity." (PMID 34097054, 2021). "Germline mutations in BUB1B were at high risk for the development of early onset colorectal cancer." (PMID 32977361, 2020). "Abnormal expression of BUB1 and BUB1B were resulted in the prognosis of patients with brain tumor, glioblastoma, colorectal cancer, and NSCLC, and resulted in the impairment of mitotic checkpoint function." (PMID 33186389, 2020). "Furthermore, colorectal cancer patients showing Bub1 and Bub1b upregulation have a shorter relapse-free survival with respect to the groups showing normal expression of these genes." (PMID 26009897, 2015). "BUB1B perfoms a role in the inhibition of APC expression, established as a tumor suppressor gene in most colorectal cancers." (PMID 30778371, 2019).
glioblastoma (22 papers, 2011 to 2025). The most malignant astrocytic tumor (WHO grade IV). "Increased expression of BUB1B in glioblastoma is associated with tumor proliferation both in vitro and in vivo." (PMID 35847923, 2022). "Additionally, BUB1B overexpression has been linked to increased tumorigenicity and resistance to radiotherapy in glioblastoma." (PMID 40076684, 2025). "The interaction of BUB1b with FOXM1 enhanced radiotherapy resistance in glioblastoma." (PMID 39043653, 2024). "BUB1B, a crucial mitotic spindle checkpoint, is overexpressed in adrenocortical carcinomas and promotes tumor proliferation while inducing radio resistance in glioblastoma." (PMID 38144520, 2023). "An aberrant expression of BUB1B had been reported in various cancers including ductal breast carcinoma (DBC), glioblastoma (GBM), and pancreatic ductal adenocarcinoma (PDAC)." (PMID 35068350, 2022). "We established that Msi1 levels affect the expression of Bub1, Bub1B, MADL1 and CDC20 and Bub3 is a direct target of Msi1 in glioblastoma cells." (PMID 33804958, 2021). "It has been found that numerous tumors, such as glioblastoma and gastric adenocarcinoma, harbor expression changes in BUB1, BUB1B, and TTK as well as checkpoint dysfunction." (PMID 32090084, 2020). "BUB1B gene expression was significantly increased in GBM patients (p= 2.2E-20, fold change 3.856, number of samples: normal brain n=23, glioblastoma n=81)." (PMID 25576921, 2015).
lung adenocarcinoma (22 papers, 2015 to 2025). A carcinoma that arises from the lung and is characterized by the presence of malignant glandular epithelial cells. "Our study has demonstrated an association between BUB1B expression and poor prognosis, as well as immune regulation, in lung adenocarcinoma, suggesting a potential role in facilitating tumor immune evasion." (PMID 40076684, 2025). "Overexpression of BUB1B is associated with disease progression and poor survival in human lung adenocarcinoma patients." (PMID 26000094, 2015). "In addition, overexpression of BUB1B was associated with disease progression and poor overall survival in human lung adenocarcinoma patients." (PMID 26000094, 2015). "In conclusion, our comprehensive pan-cancer analysis demonstrated that BUB1B is aberrantly expressed across various cancer types, with its expression levels significantly associated with clinicopathological characteristics and patient prognosis, particularly in lung adenocarcinoma." (PMID 40076684, 2025). "This study seeks to offer a systematic and comprehensive analysis of the role of BUB1B in the progression of various cancers, with a particular focus on lung adenocarcinoma, utilizing a range of databases." (PMID 40076684, 2025). "This study underscores the potential of BUB1B as a biomarker and a promising therapeutic target for patients with lung adenocarcinoma." (PMID 40076684, 2025). "Subsequently, we selected lung adenocarcinoma (LUAD) to further investigate the biological function of BUB1B using the LinkedOmics database." (PMID 40076684, 2025). "BUB1B was involved in the acute inflammatory response and IgA production pathways but negatively correlated with inflammation in lung adenocarcinoma." (PMID 40076684, 2025). "It has been reported that the expression of BUB1B was positively related to the cell cycle and glycolysis in lung adenocarcinoma." (PMID 38711083, 2024). "BUB1B has been identified as a molecular target for lung adenocarcinoma regulating anchorage‐independent growth, anoikis, and metastasis by research studies." (PMID 38344410, 2024). "BUB1B overexpression drives cancer progression and recurrence, promoting anchorage-independent survival and facilitating lung adenocarcinoma metastasis." (PMID 38410481, 2024). "Specifically, BUB1B is required for anchorage-independent growth in soft agar and anoikis resistance in suspension cultures of lung adenocarcinoma cell lines." (PMID 26000094, 2015). "Collectively, these data reveal a novel function for BUB1B in mediating anchorage-independent survival and growth, thereby facilitating lung adenocarcinoma dissemination during metastasis." (PMID 26000094, 2015). "In contrast to these findings, we found that our mutant Kras-driven lung adenocarcinoma cell lines were viable in 2D culture following BUB1B knockdown." (PMID 26000094, 2015). "We observed that while BUB1B knockdown reduced anchorage-independent growth of all human lung adenocarcinoma and colon cancer cell lines that we tested, those harboring KRAS mutations were slightly more sensitive." (PMID 26000094, 2015). "We further examined genomic changes at the BUB1B locus in patient samples from the TCGA lung adenocarcinoma data set." (PMID 26000094, 2015). "In human lung adenocarcinoma patients, higher levels of BUB1B expression were found in later stages of disease and lymph node metastases." (PMID 26000094, 2015). "In this study we showed that knockdown of BUB1B/BUBR1, a critical mitotic checkpoint protein, significantly inhibited anchorage-independent growth of lung adenocarcinoma cell lines." (PMID 26000094, 2015). "Additionally, we assessed BUB1B’s impact on lung adenocarcinoma proliferation and migration through CCK-8, wound healing, transwell assays and Western blot analysis." (PMID 40076684, 2025).
lung adenocarcinoma (continued). "During lung adenocarcinoma metastasis, BUB1B may regulate anchorage-independent proliferation and survival, which will aid in the tumor's dissemination." (PMID 39911278, 2025). "BUB1B knockdown could decrease the glycolysis-related genes, including solute carrier family 2 number 1, LDHA, pyruvate kinase M 2, and hexokinase 2, suggesting that BUB1B acts as an activator in glycolytic metabolism to promote lung adenocarcinoma." (PMID 38711083, 2024). "Our report is the first to identify a role for BUB1B in lung adenocarcinoma and to indicate that anchorage-independent growth and anoikis resistance may be a potential mechanism by which this occurs in lung adenocarcinoma." (PMID 26000094, 2015). "In summary, we have elucidated a previously unknown function of BUB1B in progression of lung adenocarcinoma through mediating anchorage-independent survival and growth." (PMID 26000094, 2015). "Here we identify a novel role for BUB1B in lung adenocarcinoma progression." (PMID 26000094, 2015). "We further examined the effect of BUB1B knockdown in multiple human lung adenocarcinoma cell lines." (PMID 26000094, 2015). "However, the potential mechanism by which BUB1b orchestrates the progression of lung adenocarcinoma (LUAD) remains unclear." (PMID 39043653, 2024). "Thus, targeting BUB1B could provide potential therapeutic benefit in suppressing metastasis and prolonging survival in lung adenocarcinoma patients." (PMID 26000094, 2015). "However, it remains to be determined whether these cancers share a similar mechanism of action from BUB1B overexpression as lung adenocarcinoma." (PMID 26000094, 2015). "A large-scale analysis of the transcriptional profile of NSCLC suggested that BUB1B is a hub gene in adenocarcinoma (ADC, lung adenocarcinomas)." (PMID 37808164, 2023). "Notably, BUB1B demonstrated a negative correlation with the inflammatory status in most tumors, with lung adenocarcinoma (LUAD) being the most prominent example." (PMID 40076684, 2025). "Finally, BUB1B is overexpressed in the vast majority of human cancers and knockdown of BUB1B also significantly reduced AIG in cell lines derived from several other cancer types in addition to lung adenocarcinoma." (PMID 26000094, 2015).
hepatocellular carcinoma (21 papers, 2018 to 2025). A malignant tumor that arises from hepatocytes. "Nevertheless, the precise biological role and underlying mechanisms of BUB1B in hepatocellular carcinoma (HCC) remain indistinct." (PMID 32977361, 2020). "For instance, BUB1B contributes to the progression of hepatocellular carcinoma by activating the mTORC1 signaling pathway." (PMID 40076684, 2025). "BUB1B promotes hepatocellular carcinoma progression via activation of the mTORC1 signalling pathway." (PMID 39628446, 2024). "The next hub gene BUB1B was involved in the progression of hepatocellular carcinoma (HCC) by activating mTORC1 signaling pathway." (PMID 36900109, 2023). "BUB1B also promotes the progression of hepatocellular carcinoma by activating the mammalian target of the rapamycin complex 1 (mTORC1) signaling pathway." (PMID 34298705, 2021). "Additionally, BUB1B contributes to the progression of hepatocellular carcinoma by activating the mTORC1 signaling pathway." (PMID 40076684, 2025). "For example, BUB1 can enhance the proliferation of hepatocellular carcinoma cells by activating the phosphorylation of SMAD2, and BUB1B promotes liver cancer progression by activating the mechanistic target of rapamycin complex 1 (mTORC1) signaling pathway." (PMID 35493295, 2022). "Adopting a series of bioinformatics analysis methods, the current study identified 763 DEGs and seven hub genes (CDC20, CDK1, MAD2L1, BUB1, BUB1B, CCNB1, and CCNA2) that may be involved in hepatocellular carcinoma tumorigenesis and progression." (PMID 33767726, 2021). "Following the synthesis of CCNB1, CDC20, CDC7, BUB1B, and MCM3 have been examined in hepatocellular carcinoma (HCC) samples." (PMID 36497125, 2022).
lung carcinoma (18 papers, 2009 to 2025). "Bioinformatics analyses have revealed that the overexpression of BUB1B is associated with an unfavorable prognosis in liver cancer, pancreatic cancer, and lung cancer based on the TCGA database." (PMID 34616422, 2021). "Finally, to investigate the biological function of BUB1B in lung cancer progression, we subsequently performed loss-of-function experiments and silenced the expression of BUB1B in the human LUAD cell line A549." (PMID 40076684, 2025). "While a previous study reported the oncogenic role of BUB1b in lung cancer, the underlying mechanism of BUB1b-mediated progression remains unclear." (PMID 39043653, 2024). "Previous studies discovered that over-expression of BUB1B in tumor tissues predicts a poor prognosis of pancreatic ductal adenocarcinoma and adrenal carcinoma, while the low expression of BUB1B is associated with poor survival in patients with colon adenocarcinoma and lung cancer." (PMID 34257537, 2021). "In conclusion, the findings of the present study indicate that BUB1B expression significantly influences the progression of lung cancer." (PMID 40076684, 2025). "While bioinformatics analysis offer valuable insights into the role of BUB1B in malignancies, we substantiated its tumor promoting function in lung cancer through molecular biology techniques." (PMID 40076684, 2025). "Various studies have confirmed the aberrant level of BUB1b in different kinds of cancers, including lung cancer." (PMID 39043653, 2024). "We analyzed lung cancer cohorts with KRAS mutations (GSE31210) and found that higher hub gene levels (BUB1, BUB1B, NCAPG, CDC20, CDK1, KIF11) were significantly associated with worse OS in lung cancer patients with KRAS mutations." (PMID 36176446, 2022). "Low expression of BUB1B contributes to poor survival and metastasis in human colon adenocarcinomas and lung cancer, while overexpression of BUB1B is related to progression and recurrence of gastric cancer, bladder cancer, HCC, and many other cancers." (PMID 30363964, 2018). "Correspondingly, we found that knockdown of BUB1B also significantly reduced AIG in human cell lines derived from several cancer types other than lung cancer." (PMID 26000094, 2015). "Moreover, the siRNA-mediated knockdown of BUB1B resulted in the inhibition of proliferation and migration of lung cancer cells in vitro." (PMID 40076684, 2025). "Consequently, BUB1B holds potential as a biomarker for predicting patient prognosis and the efficacy of anticancer therapies in lung cancer." (PMID 40076684, 2025). "Notably, certain genes, such as CTLA4, MZB1, NIP7, and BUB1B in ADC, as well as GNG11 and CCNB2 in SCC, were found to be associated with tumor size, adding a crucial dimension to our understanding of lung cancer biology." (PMID 38612418, 2024). "Low expression of BUB1B contributes to poor survival and metastasis in human colon adenocarcinomas and several lung cancer cell lines, while overexpression of BUB1B is related to progression and recurrence of gastric cancer, bladder cancer, liver cancer, and many other cancers." (PMID 30765611, 2019). "CENPF (Centromere protein F) is a gene related to chromosome segregation during mitosis that reduces overall survival in lung cancer and is a hub gene (AURKB, BUB1B, KIF2C, HMMR, CENPF, and CENPU) overexpressed in cancer patients." (PMID 36661515, 2023). "Some of the predicted master regulators, including PTTG1, RFC4, TRIP13, BUB1B, TTK, and ZWINT are capable of promoting migration, invasion, and metastasis of lung cancer cells." (PMID 36304306, 2022). "Compared to primary lung cancer, all the expression of hub genes increased in lymph node metastasis samples, and the expression of BUB1, BUB1B, CDK1, CCNA2 and CDC20 were related to peritoneum metastasis." (PMID 36176446, 2022).
bladder cancer (17 papers, 2010 to 2025). "Herein, we identified an aberrant BUB1B/BUBR1 expression in CRT-recurrent clones in bladder cancer (BC) by comprehensive proteomic analysis." (PMID 34545188, 2021). "Overexpression of BUB1B was significantly correlated with worse clinicopathological characteristics, which predicted tumor recurrence and progression in bladder cancer." (PMID 32977361, 2020). "Meanwhile CCNB1, CENPF and BUB1B genes were revealed to be positively co-expressed with ANLN in bladder cancer from three different datasets." (PMID 28600503, 2017). "To evaluate the significance of the five proteins in bladder cancer, we investigated the relationship between the expression of the five proteins (BUB1B, CCNB1, CDC25A, FBXO5, NDC80) and clinicopathological features." (PMID 29246203, 2017). "For instance, overexpression of BUB1B is related to chromosomal instability in bladder cancer." (PMID 32977361, 2020). "We performed protein-protein interaction analysis to select five important candidate genes (BUB1B, CCNB1, CDC25A, FBXO5, KIF20A, NDC80) regulated by PLK1 in bladder cancer cells using STRING software." (PMID 29246203, 2017). "Four genes (BUB1B, CCNB1, CDC25A and NDC80) were expressed at higher levels in bladder cancer tissues than in normal bladder tissues, but the expression of FBXO5 was lower in bladder cancer than in normal tissues." (PMID 29246203, 2017).
gastric cancer (16 papers, 2007 to 2023). A primary or metastatic malignant neoplasm involving the stomach. "Moreover, Bub1 and Bub1b expression levels are drastically upregulated in gastric cancer associated with tumor cell proliferation." (PMID 26009897, 2015). "The most shared rewiring hubs are BUB1B (brain, lung-adeno, kidney-clear, kidney-papillary and stomach cancer), CYP11A1 (bladder, brain, kidney-clear and uterus cancer) and CCNB1 (brain, kidney-papillary, lung-adeno and lung-squamous cancer)." (PMID 31396397, 2019).